CTLA4 (cytotoxic T-lymphocyte associated protein 4)
Diseases named in the same sentence as CTLA4 in open-access papers (continued):
Sharing a sentence is not in itself a finding about the gene and the disease.
melanoma (continued). "In preclinical melanoma models, the combination of Ganetespib and a CTLA-4 inhibitor has shown anticancer effects in melanoma and colon cancer models through a decrease in immunosuppressive regulatory T cells and an increase in the antitumor activity of CD8+ T cells." (PMID 40872476, 2025). "The most effective results of a combined anti-PD-1 and anti-CTLA4 immunotherapy was reported to be a 7-year intracranial progression-free survival in 42% of patients with active asymptomatic melanoma brain metastasis which appeared to keep the tumor under control rather than eliminating it." (PMID 40760097, 2025). "A novel therapeutic strategy for advanced locoregional melanomas using anti-programmed cell death protein 1 (PD-1) and anti-cytotoxic T-lymphocyte antigen 4 (CTLA-4) immunotherapy has shown efficacy as a preoperative treatment to enhance cure rates and shorten the duration of systemic therapy." (PMID 40028040, 2025). "Melanoma has been treated with drugs related to immune targets such as CTLA-4, PD-1, and LAG-3." (PMID 40429702, 2025). "Indeed, it has been shown that CTLA4 can be expressed by human melanoma cell lines and patients suffering from melanoma." (PMID 40563506, 2025). "Ipilimumab is the first CTLA-4 inhibitor approved for melanoma treatment, used in metastatic disease and as an adjuvant for stage III melanoma, enhancing T-cell activity by blocking the interaction between CTLA-4 and B7 molecules, thus promoting the immune system’s attack on tumor cells." (PMID 41346595, 2025). "To investigate potential immunotherapy responses in SCLC subtypes, we performed SubMap analysis by comparative gene expression profiling between a publicly available cohort of 47 melanoma patients treated with anti-PD-1 and anti-CTLA-4 and the SCLC ferroptosis subtype." (PMID 40433367, 2025). "A retrospective, multicenter study using TriNetX identified adult melanoma patients receiving anti-PD-1 monotherapy (pembrolizumab or nivolumab) (Cohort 1: n = 10,586) and patients receiving anti-PD-1/CTLA-4 combination therapy (nivolumab + ipilimumab) (Cohort 2: n = 5,705)." (PMID 40351833, 2025). "Emerging evidence suggests that melanomas harboring ROS1 mutations may exhibit heightened sensitivity to immune checkpoint inhibitors (ICIs), including PD-1 and CTLA-4 inhibitors." (PMID 40508177, 2025). "While ICIs such as anti-PD-1, anti-PD-L1, and anti-CTLA-4 have shown remarkable success in prolonging survival in cancers like melanoma and lung cancer, they simultaneously disrupt immune homeostasis, leading to unintended immune activation against healthy tissues." (PMID 40606990, 2025). "In our experimental setup, the observed reduction of specifically bound MB with VEGFR2-targeted CEUS under anti-PD-L1/anti-CTLA-4 immunotherapy of malignant melanoma may be explained by the pathophysiological connection between VEGF and tumour immunology." (PMID 40591551, 2025). "The B16F0 melanoma in the vaccinated mice was additionally treated by a CTLA-4 checkpoint blockade." (PMID 40650228, 2025). "Despite this clinical uncertainty, analysis of malignant melanoma patients responsive to anti-CTLA-4 ipilimumab therapy who were monitored over a period of more than 10 years revealed that they appear to have gained long-term protection, supporting the possibility of a post-tumour vaccine effect." (PMID 40265076, 2025). "Similarly, immune checkpoint blockade using anti-CTLA-4 antibodies has been shown to induce effective T cell-mediated antitumor immune responses, with clinical benefits reported in patients with melanoma." (PMID 40463388, 2025). "Anti-PD-1 agents (nivolumab and pembrolizumab), anti-CTLA-4 therapy (ipilimumab), and combination regimens involving both checkpoints (nivolumab–ipilimumab) have become approved treatment options for melanoma, driven by the promising clinical outcomes of immune checkpoint inhibition." (PMID 41584608, 2025).
melanoma (continued). "As a result, melanomas may experience an ineffective T cell response and subsequently resistance to T cell-based immunotherapies such as anti-PD-L1 and anti-CTLA-4." (PMID 41369373, 2025). "Conversely, RNA-seq data from melanoma patients undergoing anti-CTLA-4 therapy revealed a significant downregulation of GSDMD post-treatment (log2FC = -1.1007, p = 0.021), suggesting dynamic modulation of GSDMD in response to distinct immune checkpoint inhibitors." (PMID 40491921, 2025). "In these ROIs tumors of the BM group overexpressed CTLA-4 compared to melanomas from the OOM group." (PMID 40621453, 2025). "Summary of mechanism-based CTLA-4/PD-1 combination strategies in melanoma brain metastases (MBM)." (PMID 40666508, 2025). "Immune checkpoint inhibitors (ICIs), such as PD-1/PD-L1 and anti-CTLA-4 therapies, demonstrated clinical efficacy in the treatment of various malignancies including melanoma, renal cell carcinoma, otorhinolaryngological cancers, and lung cancer as non-small cell lung cancer." (PMID 40559409, 2025). "Notably, patients with immune-inflamed melanomas generally exhibit greater overall survival (OS) and PFS when receiving anti-PD-1 or anti-CTLA-4 immunotherapy than those with melanomas categorized into the immune-desert type." (PMID 40108693, 2025). "Interestingly, CTLA‐4 mRNA was detected in melanoma cells of 75% tested canine OMs, with low expression levels." (PMID 39789732, 2025). "Both JAK1 and JAK2 knockout melanoma cells are insensitive to anti-PD-1 and anti-CTLA-4 therapy." (PMID 40108693, 2025). "Mice colonized with responder NSCLC stool and subsequently colonized with a sarcoma line also responded to anti–CTLA-4 therapy, and we have observed that mice colonized with responder melanoma stool and subsequently implanted with a colon carcinoma also respond to anti–PD-L1 therapy." (PMID 39895632, 2025). "Our study suggests that the association between pretreatment levels of ETV4 and the efficacy of anti-PD-1/anti-CTLA-4 therapy may be explained by the positive regulation of PD-L1 expression by ETV4 in melanoma." (PMID 41502516, 2025). "In other words, NDV can enhance the capability of CTLA-4 inhibitor on conquering tumor metastasis and improving long-term survival of mice with colon cancer or melanoma, by increasing tumor infiltration with activated lymphocytes, and systemic tumor inflammatory effects." (PMID 41024300, 2025). "Beyond melanoma, CTLA-4 blockade is under investigation across multiple tumor types." (PMID 41586193, 2025). "Notably, SGC3027 has been shown to enhance antitumor immune responses and improve the efficacy of ICBs such as CTLA-4 and PD-1 in melanoma models." (PMID 41204384, 2025). "In addition, in melanoma, high TMB was associated with clinical benefit in patients receiving ipilimumab alone (anti-CTLA-4)." (PMID 40148586, 2025). "Similarly, combination therapy with nivolumab and ipilimumab (anti-CTLA-4) significantly enhances overall survival, highlighting its effectiveness against resistance mechanisms in advanced melanoma." (PMID 40868149, 2025). "Besides, clinical trials combining IDO1 inhibitors with CTLA-4 blockade in melanoma patients reported toxicities, leading to the discontinuation of some studies." (PMID 41233805, 2025). "Moreover, a recent study in melanoma patients revealed that anti-CTLA-4 induces a robust clonal expansion of progenitor exhausted T cells which, in turn, promotes exhausted T cell reinvigoration when combined with anti-PD-1 treatment." (PMID 40342408, 2025). "In humans, transcriptome analysis of melanoma samples revealed a strong association between high expression of MLKL and prolonged overall survival and durable clinical response to immunotherapy with anti-PD-1 and/or anti-CTLA-4 checkpoint inhibitors." (PMID 40345706, 2025).
melanoma (continued). "In a study of advanced melanoma, it was demonstrated that the combination of local chemotherapy (nitrogen mustard alkylating agent melphalan) and anti-CTLA-4 improved response rate and progression-free survival (PFS) through enhancing the infiltration of T cells to the tumor site." (PMID 40342408, 2025). "An analysis of baseline blood samples from 140 melanoma patients treated with anti-CTLA-4 therapy found that only low baseline IL-6 levels (< 2.5 ng/L) and female sex were correlated with an increased risk of Grade ≥ 3 irAEs after adjustment for follow-up time." (PMID 40632185, 2025). "However, anti-PD-1 and anti-CTLA-4 were only effective in one melanoma cell line, suggesting variable responses." (PMID 40361336, 2025). "In addition, the melanoma patients with combined anti-PD-1 and anti-CTLA-4 therapies revealed PD-1-expressing CD4+FOXP3- T cells (4PD-1hi), a unique suppressive T cell subset linked to higher tumor burden." (PMID 40857744, 2025). "In addition, melanomas with brain metastases (BM) showed higher expression levels of fibronectin, CTLA-4, CD27, and PanCK compared to tumors with metastases in other organs (OOM)." (PMID 40621453, 2025). "Furthermore, the combination of OX40 co-stimulation or CTLA-4 blockade with melanoma-specific CD4+ T cell therapy achieves comprehensive tumor elimination, including targeting antigen escape variants." (PMID 40661781, 2025). "Importantly, lower levels of XBP1s, ATF4, and BiP expression in pre-treatment tumor biopsy samples significantly correlated with better treatment responses and prolonged survival in different groups of melanoma patients undergoing anti-CTLA-4 therapy." (PMID 41372991, 2025). "Immune checkpoint inhibitors (ICIs), such as those targeting programmed death-1 (PD-1), programmed death ligand-1 (PD-L1), and cytotoxic T lymphocyte-associated antigen-4 (CTLA-4), have shown remarkable efficacy in malignancies like melanoma and non-small cell lung cancer." (PMID 40223940, 2025). "Advanced melanoma has undergone a therapeutic revolution over the course of the past two decades, driven by immune checkpoint inhibitors (ICI), targeting cytotoxic T-lymphocyte-associated protein 4 (CTLA-4) and programmed cell death-1 (PD-1), as well as BRAF-/MEK- targeted therapies." (PMID 41476990, 2025). "Moreover, high levels of SK1 expression in melanoma cells participate in resistance to ICI (anti-PD-1 or anti-CTLA-4) in preclinical melanoma models." (PMID 39136013, 2024). "DNA-PKi confers PD-1/CTLA-4 ICB efficacy against established B16-F10 melanoma tumors." (PMID 39436696, 2024). "The antitumor activity of anti-CTLA-4 antibody monotherapy has been demonstrated in melanoma." (PMID 39354625, 2024). "Ipilimumab, the first monoclonal antibody targeting CTLA-4, has been the subject of extensive research involving 2901 patients across 25 clinical trials, demonstrating durable responses and prolonged survival in advanced melanoma cases." (PMID 39769318, 2024). "Indeed, shotgun MG-based taxonomic composition of feces at baseline was associated with objective response rates in patients with stage IV melanoma treated with anti-PD-1 alone or combined to anti-CTLA-4 in several independent cohorts." (PMID 38395948, 2024). "On the other hand, in melanoma, CTLA4 plays a complex role in modulating tumor immunity." (PMID 39336572, 2024). "Overall, the behavior of Tsurv remained stable pre-ICIs or post-ICIs, regardless of whether it was administered in combination with anti-PD-1 or anti-CTLA-4 therapy for melanoma." (PMID 38343549, 2024). "Aligning with our hypothesis, we found that combining CTLA-4 blockade with LDHi delays tumor progression in B16 melanoma and MC38 colon cancer more effectively than using each agent alone." (PMID 39225102, 2024).
melanoma (continued). "The therapeutic effects of anti-CTLA4 antibodies in mice with melanoma were also observed in experiments in which data from colitis and tumor models were compared to mice receiving anti-CTLA4 antibodies similar to ipilimumab patients, consistent with clinical observations." (PMID 38564002, 2024). "In a murine model of melanoma, the combination of chemotherapy and CTLA-4 blockade induced a cellular shift in the local tumor microenvironment, with infiltrating CD8 + and CD4 + T cells increasing the CD8 + /Foxp3 T-cell ratio and leading to an improved survival." (PMID 37843790, 2024). "A significant reduction in PD-L1 mRNA and protein levels in A375 and SK-MEL-28 melanoma cell lines in vitro, as well as effective suppression of B16-F10 melanoma lung metastases by combination therapy with checkpoint inhibitors (anti-PD-1 and/or anti-CTLA-4), has been shown in mouse models in vivo." (PMID 39594665, 2024). "The use of ipilimumab (anti-CTLA-4 mAb) either alone or in combination with nivolumab (anti-PD-1 mAb) is currently approved for the treatment of melanoma, colorectal cancer (CRC), hepatocellular carcinoma (HCC), non-small cell lung cancer (NSCLC), and renal cell carcinoma (RCC)." (PMID 38375475, 2024). "Both CD4+ and CD8+ T cells induced Ki67 in a flow cytometric analysis of pre- and post-therapy PBMC samples from 48 MM patients and mouse melanoma models treated with CTLA-4 and PD-1 blockade combinations and monotherapy, with the Ki67+ cells exhibiting a CD45RO+ memory phenotype." (PMID 39273452, 2024). "Dysfunctional CD8+ T cells are characterised by expressing different inhibitory molecules, such as LAG3, PDCD1 (encoding PD-1), CXCL13, HAVCR2 (encoding Tim3), ENTPD1 (encoding CD39), CTLA4, and TIGIT, which are all less expressed in memory-like T cells in melanoma." (PMID 38893071, 2024). "No prospective data were available prior to 2021 to inform selection between combination BRAF and MEK inhibition versus dual blockade of programmed cell death protein-1 (PD-1) and cytotoxic T lymphocyte antigen-4 (CTLA-4) as first-line treatment options for BRAFV600-mutant melanoma." (PMID 38167503, 2024). "Anti-CTLA-4 immunotherapy is an FDA-approved treatment for advanced melanoma." (PMID 39204136, 2024). "Thus, we reviewed publicly available exome-sequencing data from patients with melanoma undergoing CTLA-4 or PD-1 blockade therapy to investigate potential correlations between PRKDC levels and response to checkpoint therapy." (PMID 39436696, 2024). "Similarly, the combination of radiotherapy with anti-CTLA4 or anti-PD-L1 has been evaluated in studies, demonstrating a more effective induction of antitumor immunity against melanoma cells." (PMID 39534873, 2024). "They suggested that inhibiting H3K27me3 in T cells using CPI-1205 could enhance the efficacy of anti-CTLA-4 therapy in bladder cancer and melanoma." (PMID 39080807, 2024). "Additional melanoma trials have also combined sargramostim with CTLA-4 inhibition." (PMID 38339253, 2024). "However, the blockade of CTLA-4 resulted in a noticeable increase in the number of detectable melanoma-specific CD8+ T cell." (PMID 38500876, 2024). "However, Treg, especially eTregs (with greater suppressive capacity), which have been extensively correlated with poor prognosis in several tumors, including melanoma, have been shown to hinder responses mediated by anti-PD-1 therapy and anti-CTLA-4." (PMID 39273452, 2024). "Primary targets in melanoma treatment are PD-1, PD-L1, and CTLA-4." (PMID 38715609, 2024). "Further resembling Gc-/- mice, fecal transplants from WT mice that were fed with VitD3 high diet increased the therapeutic efficacy of anti-CTLA-4 and anti-PD-1 immune checkpoint blockade inhibitors in transplantable cancer models other than 5555 BrafV600E melanoma such as MCA-205 and MC38." (PMID 38662827, 2024).
melanoma (continued). "The CTLA-4 inhibitor is called ipilimumab, and PD-1 inhibitors include nivolumab and pembrolizumab, which are often used in melanoma therapies and can be used synergistically, as CTLA-4 mainly suppresses immune response in lymph nodes, whereas PD-1 does so in peripheral tissues." (PMID 39519055, 2024). "Indeed, when IR is combined with immunotherapy using the anti-CTLA4 monoclonal antibody, ipilimumab, AEs have occurred in melanoma and metastatic non-small cell lung cancer." (PMID 38678042, 2024). "These proliferating cells, in addition to the PD1 molecule, expressed high levels of CTLA-4, and this phenomenon makes these cells particularly relevant in the anti-tumor immunity when the anti-PD1 therapies were combined with the anti-CTLA4 antibodies, as shown in melanoma patients." (PMID 39744631, 2024). "Ipilimumab (anti-CTLA-4) was FDA-approved in 2011 for melanoma, and this was rapidly followed by the development of monoclonal antibodies targeting PD-1 (pembrolizumab and nivolumab) and PD-L1 (atezolizumab and durvalumab), which were approved in 2014 and 2019 respectively." (PMID 39247203, 2024). "Moreover, a marked increase in class-switched memory B cells, plasmablasts and CD21low B cells was observed after the first cycle of combined administration of anti-PD-1 and anti-CTLA-4 mAbs in melanoma patients." (PMID 38318190, 2024). "Immune checkpoint inhibitors (ICIs), which boost the immune system’s capacity to attack cancer cells by blocking immune checkpoint proteins like PD-1 and CTLA-4, have achieved remarkable success across various cancer types, including melanoma, lung, and gastric cancers." (PMID 38654165, 2024). "Additionally, a novel melanoma-stem-cell vaccine has been developed that can suppress the expression of CTLA-4, PD-1, and TIM-3 and delay the progression of melanoma by inducing antitumor immune responses." (PMID 38732242, 2024). "The concept of dual PD-1/CTLA-4 blockade is successfully applied for the treatment of melanoma." (PMID 38515578, 2024). "Therefore, treatment options for melanoma patients who relapse to both anti-PD-1 and anti-CTLA4 ICIs after their combinatorial or sequential administration remain limited for many years." (PMID 39435288, 2024). "Since the advent of immunotherapy, unprecedented successes have been achieved in melanoma therapy by application of anti-programmed cell death protein 1 (PD-1) antibodies (pembrolizumab and nivolumab) and anti-cytotoxic T-lymphocyte protein 4 (CTLA-4) antibodies (ipilimumab)." (PMID 39700646, 2024). "Site of primary melanoma was cutaneous skin or unknown primary, except three cases from patients with primary mucosal melanoma that were resistant to anti-CTLA4." (PMID 38594286, 2024). "Moreover, seminal clinical studies have demonstrated the efficacy of anti-CTLA-4 and anti-PD-1 as combination therapy to treat advanced stage melanoma patients." (PMID 39247203, 2024). "In a cohort of 271 patients with melanoma, treatment with sequential anti-CTLA-4 and anti-PD-1 was associated with a better survival outcome than monotherapy with anti-PD-1 or anti-CTLA-4, anti-PD-1 followed by anti-CTLA-4 or dual immunotherapy." (PMID 38448521, 2024). "Compared to anti-CTLA-4 immune checkpoint inhibitors, nivolumab has demonstrated therapeutic benefit against a broader spectrum of malignancies, in addition to its effectiveness in treating melanoma." (PMID 39127974, 2024). "A recent evaluation of melanoma patients receiving combination anti-CTLA-4 and anti-PD-1 found that increased IL-17a/IL-17f signaling was positively associated with immune infiltration and improved clinical outcomes; however, this relationship did not extend to patients treated with monotherapy." (PMID 39403935, 2024). "In our study, although chemoimmunotherapy was not compared to chemotherapy alone, chemotherapy may fulfil the priming effect that has been achieved by anti-CTLA-4 in melanoma." (PMID 38406805, 2024).